CD4 (CD4 molecule)
Diseases named in the same sentence as CD4 in open-access papers (continued):
Sharing a sentence is not in itself a finding about the gene and the disease.
cancer (continued). "We discovered that JMJD8 presented strong positive correlations with M2 macrophages in TGCT, BRCA, and LGG and negative correlations with M1 macrophages and activated CD4+ memory cells in many cancers." (PMID 35898493, 2022). "Unlike monocyte-derived TAM10, cancers use B-MF to mediate escape and metastasis via suppressing antitumor IFNγ+CD4+ T cells." (PMID 36104343, 2022). "In general, peptide-based cancer vaccines require both CD8+ and CD4+ T-cell epitopes." (PMID 36560420, 2022). "In addition, CD4 + T cells often differentiate into helper T cells, producing cytokines, and cooperating with CD8 + T cells to kill cancer cells." (PMID 35996170, 2022). "PAs were able to protect normal activated CD4+ T lymphocytes but not Jurkat or K562 cancer cell lines due to the action of Dox, Cis, or Irt." (PMID 35163785, 2022). "CXCL9, CXCL10, and CXCL11 are ligands of the chemokine receptor CXCR3, which is preferentially expressed by CD4+ and CD8+ T cells, but could also be detected on the surfaces of cancer cells." (PMID 36428508, 2022). "While T helper and T regulatory cell responses have been extensively characterized in trials consisting of several vaccine regimens, studies evaluating CD4 CTL expansion/induction and their clinical relevance upon therapeutic vaccination in cancer remain scant." (PMID 35572552, 2022). "In our study, NEIL3 is positively correlated with six types of immune cell infiltration, including B cells, CD4 T cells, CD8 T cells, neutrophils, macrophages, DCs in KIPAN, KIRC, and LIHC, indicating that these three types of cancers may be inflamed tumors." (PMID 36612106, 2022). "However, the microenvironment of pMMR tumors still presents activation on prime antigen-specific CD4 and CD8 T cells of cancer immunity." (PMID 35311077, 2022). "The fraction of PD1 expressing CD4+ T lymphocytes, CD4+Foxp3− Teff cells and CD4+Foxp3+ Tregs was not significantly different from healthy controls in cancer patients before or at various time points after brachytherapy." (PMID 35804830, 2022). "Moreover, DUSP4 expression was significantly correlated with the infiltration levels of CD4+ T cells, CD8+ T cells, B cells, neutrophils, and dendritic cells in various cancer types." (PMID 35774798, 2022). "In contrast to the beneficial effects of CTLs in the vast majority of cancers, the effect of CD4+ T cell populations on clinical outcomes is not so clear." (PMID 35008422, 2022). "Moreover, IL10 released by MSDCs and TAMs favors a CD4+ Th2 response with B-cell engagement over CD4+Th1 and cytotoxic CD8+T (Tc1) responses, which are both effective cancer immunosurveillance mechanisms." (PMID 35392957, 2022). "In the present study, we demonstrated that polyamines have cytoprotective effects on normal human CD4+ T lymphocytes but not on cancer Jurkat or K562 cells." (PMID 35163785, 2022). "Most remarkable, the expression of T cell CD4+ central memory, T cell CD4+ Th1, and HIF1α has the strongest negative correlation in various cancers." (PMID 35860430, 2022). "The accumulation of T follicular helper cells (Tfh), a CD4+ T cell subset essential for B cell response shaping, can produce a negative or positive prognostic effect on multiple cancer types." (PMID 35281853, 2022). "Coculture of CD4+ T cells with CD8+ T cells did not affect apoptosis or proliferation of the cancer cells (data not shown)." (PMID 35359980, 2022). "In addition, members of the ARID family were found to be strongly related to the abundance of CD4 + T cells and CD8 + T cells, the expression of PD-L1 and the TMB value in various cancers." (PMID 35239432, 2022). "While CD8+ T cells alone showed near to no migration, adding CD4+ T cells enhanced migration towards the cancer cells." (PMID 35359980, 2022).
cancer (continued). "This dependency on PD-L1 expression could result from the direct interaction between CD4+ T cells and MHC-II, which can either reinforce the cell-killing activity of CD8+ T cells that are already engaged by MHC-I or directly kill cancer cells." (PMID 36230808, 2022). "All the analyzed carcinomas presented the infiltration of TILs CD3+, CD4+ and CD8+." (PMID 36139578, 2022). "Our initial exploration demonstrated that aberrant PHF19 expression was correlated with increased immune cell infiltration of MDSCs and Th2 subset of CD4+ T cells in the majority of cancers, which implied potential value of clinical application for PHF19 in cancer treatment." (PMID 35069553, 2021). "We discovered patients had higher CD4+CD28+/CD4+ percentage and CD4+CD28+ T cell counts than those in controls, which might imply that CD4+ T cells were activated in cancer occurrence." (PMID 34488711, 2021). "While the majority of cancer immunotherapies have traditionally focused on enhancing cytotoxic responses by CD8+ or NK cells, there are clear evidences that CD4+ T cell responses can modulate the immune response against tumors and influence the efficacy of ICI therapy." (PMID 33777008, 2021). "The core module of cytolytic effector molecules appears largely conserved across murine and human viral, human aging, and human cancer contexts: notably, GZMB+ cytotoxic CD4+ T cells co-express GZMA and often GZMH, PRF1, FGFBP2, and granule-associated proteins NKG7 and (in humans) GNLY." (PMID 34910940, 2021). "It is known that both CD4+ and CD8+ T cells may play an important role in protecting against malignant tumors." (PMID 33717073, 2021). "The T helper (Th) CD4+ T cells and the cytotoxic (Tc) CD8+ T cells are the key players that mediate the adaptive anticancer immune response and, along with TAMs, are the most abundant cells present in the TIME of several cancer types." (PMID 35096592, 2021). "We also evaluated the infiltration of CD8+ and CD4+ T cells; interestingly, the intratumoral infiltration of CD8+ T cells was markedly upregulated in p16INK4A negative cancer but was rarely identified in p16INK4A positive cancer." (PMID 33643790, 2021). "There was a higher correlation between CD3+CD4+ T cells and CD19+ B cells in cancer patients." (PMID 34712741, 2021). "CXCL10 and CXCL11 are ligands of chemokine CXCR3, which can regulate the migration, differentiation and activation of immune cells, and are related to the selective migration and linear development of CD4 + and CD8 + T cells, thereby affecting the therapeutic effect of cancer." (PMID 35087563, 2021). "Best discrimination between patients with and without cancer relapse was obtained using a cutoff value of post‐therapeutic Th17 per CD4+ T cells > 8%." (PMID 34469022, 2021). "There was obviously positive correlation between CD4/CD3 and Ki-67 in primary cancers and negative correlation between CD4/CD3 and ER in oligometastatic sites." (PMID 34858823, 2021). "Identifying the number of CD4+ T cells, CD8+ T cells, and the CD4+/CD8+ ratio in peripheral blood can thus represent the immunological state of patients with malignant tumors, and it may also be useful in predicting the prognosis of FL patients." (PMID 34336695, 2021). "Our culture successfully drives large numbers of effector and central memory CD4+ and CD8+ T cells from healthy donors and cancer patients, including MM, breast and pancreas patients, in contrast to CAR-T cells that are comprised of effector rather than memory cells." (PMID 34611479, 2021). "Further studies with larger cohort should be conducted on patients from different backgrounds and disease states (different MSAs subtypes, with and without cancer) to better elucidate the role of TIGIT+CD226+ CD4 T cell in DM." (PMID 33413573, 2021).
cancer (continued). "The presence of CD8± cytotoxic T cell, lower than that of CD4 lymphocytes, is also important, since they cooperate in prognosis improvement in HPV-positive OPSCCs, because of their ability to kill transformed cancer cells." (PMID 33769181, 2021). "PD-1+CD8+ T cells characterized by impaired effector function are frequently observed in the setting of chronic infection and malignant tumors, but our results suggest that memory PD-1hiCD8+ T cells in RASF, in concert with CD4+ T cells, play an active role in the pathogenesis of RA." (PMID 33815416, 2021). "Invading CD4+ T cells and proinflammatory cytokines prime CD8+ T cells to become effector cytotoxic T-lymphocytes (CTL), which then play a key role in eliminating cancer cells as reviewed before." (PMID 33562138, 2021). "One of these subsets, CAF-S1, has been associated with the accumulation of FOXP3+ T lymphocytes and CD4+CD25+ T lymphocytes in the tumor, both populations related with cancer cell stemness as explained in the next section, while CAF-S4 has been associated with an increase of stromal cells." (PMID 33530455, 2021). "Only 23.3% of AC patients had median CD4 counts ≥500 (cells/μL) suggesting that a large proportion did not have optimal immune status prior to cancer diagnosis." (PMID 33596943, 2021). "Nevertheless, recruitment of CD4+ activated T cells to inflammatory sites is severely compromised in double Ena/VASP knockout mice due to defective transendothelial migration, suggesting a suppressing mechanism of cancer immunity." (PMID 33573141, 2021). "Given that the period of data collection occurred earlier in the era of ART availability compared to our study, 40% of patients were not taking ART at the time of cancer diagnosis, and the median CD4 count was just over 350 cells/uL." (PMID 34344430, 2021). "We then surveyed the relationship between KDM5C alterations and common immune infiltrates including CD8+ T cells, CD4+ T cells, Tregs, dendritic cells, B cells, macrophage, MDSC, NK cells, mast cell, neutrophils, endothelial cells and CAFs across different cancer types." (PMID 33953726, 2021). "We discovered that in all experiments CD4+ T cells inhibited the cancer cell growth, resulting in about a three-fold reduction of cancer cell numbers compared to cancer cells growing without CD4+ T cells." (PMID 34439305, 2021). "The latest study including 17 HIV-positive cancer patients showed that checkpoint inhibitors seemed like to have comparable efficacy and tolerable adverse effects, and CD4+ T lymphocyte cell count and viral load were not affected." (PMID 33882973, 2021). "Moreover, this nanomaterial induced not only the activation of both CD4+ and CD8+ T cells in the tumor site but also secretion of anti-cancer-related cytokines such as IL-12 and TNF-α." (PMID 34576180, 2021). "Nonetheless, a number of shared features, and some possibly divergent programs, can be seen in cross-context comparisons of cytotoxic CD4+ T cells in cancer and non-cancer contexts." (PMID 34910940, 2021). "We found that restimulated CD4+ T cells growing either with or without cancer cells exhibited increased levels of AMPK and activated T172 P-AMPK." (PMID 34439305, 2021). "In addition to prognostic value, the association between CD36 alterations and 6 immune infiltrative cells (B cells, CD4+ T cells, CD8+ T cells, dendritic cells, macrophages, and neutrophils) across different cancer types was analyzed." (PMID 34234847, 2021). "The discovery in 2001 that CD4+ CD25+ immunosuppressive cells can be found in the blood of healthy individuals kick-started research into the presence and behavior of these cells in cancer patients." (PMID 34632244, 2021). "Interestingly, in most cancer types, KDM1A was negatively correlated with CD4+ Th1 cells and positively correlated with CD4+ Th2 cells." (PMID 34925656, 2021). "The BRM-containing class of SWI/SNF CRC and denser H3 occupancy were found on the PD-L1 locus in the CD4+ T cells grown without cancer cells." (PMID 34439305, 2021).
cancer (continued). "As the numerically dominant Treg population in the tumor microenvironment (TME), CD4+CD25+Foxp3+ cells have been extensively studied in cancers, unlike CD8+CD28− Tregs." (PMID 34831195, 2021). "In summary, CD28null senescent T-cells accumulate in cancer patients and CD8+ and CD4+ CD28null populations may both promote disease progression." (PMID 34680058, 2021). "In addition, CD4+T cells often differentiate into helper T cells, producing cytokines, and cooperating with CD8+T cells to kill cancer cells yy." (PMID 33405394, 2021). "The H3 occupancy on the PD-L1 promoter region was much more frequent in CD4+ T cells growing without cancer cells compared to CD4+ T cells co-cultured with cancer cells." (PMID 34439305, 2021). "The pattern of CD4+ cell infiltration was similar to that of CD3, with reduced infiltrate in both low- and high-grade lesions relative to normal tissue, and the greatest infiltration in cancer." (PMID 33257839, 2021). "Moreover, this positive correlation between memory B cell, CD8+ T cell, CD4+ memory activated, and macrophage M1 with LCK and CD3E was also consistent across different cancer types." (PMID 35004669, 2021). "The CD4/CD8 T-cell ratio is emerging as a relevant marker of evolution for different pathologies and therapies, including cardiovascular diseases, human immunodeficiency virus (HIV) infection, and cancer." (PMID 34038386, 2021). "This assay enables to interrogate single cell expression levels of multiple mRNA of interest such as CD4, Cd8α, IFNγ and GZMB and their spatial distribution and can be used to detect, quantitate and evaluate the frequency and function of CAR T cells and cancer cells in tissues." (PMID 34155235, 2021). "Moreover, TFAP4 levels were significantly correlated with CD4 + T and CD8 + T cell infiltration in 15 types of cancer, B cells in 12 types, neutrophils in 16 types, macrophages in 18 types and dendritic cells in 14 types." (PMID 33373169, 2021). "In contrast, the immune-rich cancer cluster (pEc3) was enriched for memory B cells and CD4+ T cells, with weak or no enrichment of cancer types." (PMID 34650042, 2021). "Similarly, GITR and Tim-3 are both highly expressed on CD4+ Tregs, and anti-GITR antibodies are currently being developed to target deleterious Tregs in cancers." (PMID 33763071, 2021). "This study also showed decreased infiltration of CD4+ T cells in mesenchymal lung cancer; however, we did not see decreased CD4+ T-cell infiltration in the EMT-high tumors of most cancer types we analyzed." (PMID 35096592, 2021). "Indeed, our data show that human cells can be readily modified with tandem minigenes using a nonviral transposon system and can present multiple antigens to neoantigen-specific CD4+ and CD8+ T cells derived from patients with cancer." (PMID 34396986, 2021). "In comparison, in T12 (restimulated CD4+ T cells growing without cancer cells), only 504 genes were specifically upregulated." (PMID 34439305, 2021). "In contrast to currently employed checkpoint inhibitor cancer immunotherapies such as pembrolizumab and nivolumab, CD4+ T cells are not required for this effect of UMCD6." (PMID 33497367, 2021). "IL‐24 has been shown to promote the populations of CD4+ and CD8+ T cells in diverse cancer models." (PMID 33274495, 2021). "Interestingly, HER3 is highly expressed in cancer cells (CD45−/EpCAM+/E-CAD+), but limitedly in T cells (CD45+/CD8+/CD4+)." (PMID 33888713, 2021). "No significant reduction in the rates of cancers was observed in relation to sex, starting of follow up, child's origin, use of cART, VL, and CD4+ T-lymphocyte percentage." (PMID 34336735, 2021). "Because large-scale essentiality datasets were not available for CD4+ T cells, we used essentiality datasets available for different human cancer cell lines." (PMID 33483502, 2021).
cancer (continued). "Moreover, the discovery of CD4/CD8-p56lck and its targets ITAMs and CD28 has led to the application of this knowledge in the design on CARs presently in use in cancer immunotherapy." (PMID 33791292, 2021). "Although there was a trend of increasing odds of cancer by severity of CD4 nadir, none passed the threshold for statistical significance in this cohort." (PMID 33803641, 2021). "Tregs are a unique subset of CD4+CD25+ T lymphocytes and are augmented in various cancers." (PMID 34722304, 2021). "Therefore, we explored associations of CDK2/4/6/STAT3 expressions with infiltrating immune cells (CD4+ T cells, B cells, CD8+ T cells, neutrophils, dendritic cells, and macrophages) in multiple cancers." (PMID 33668805, 2021). "Lower CD4 count (≤200 cells/μL) is known to be a key factor in anal HSIL and cancer development." (PMID 33596943, 2021). "In addition, about 20 cancer types were relevant to resting memory CD4 T cells, such as KIRC which UBE2C, and resting memory CD4 T cells were negatively correlated." (PMID 34950739, 2021). "Similarly, several studies have shown the importance of the ratio between CD4+ /, CD8+ / or CD3+ and FOXP3+ cells as being crucial in predicting prognosis of cancer patients." (PMID 34493268, 2021). "After completing the T-cell maturation process by DCs, CD4+ and CD8+ T cells are differentiated to the helper T cell (Th) and cytotoxic T cell (Tc) to establish the long-lasting therapeutic effect against the cancer cells." (PMID 34576180, 2021). "The percentage of cancer cells was positively correlated with the percentage of CD8+ T cells (r = 0.6025, p = 0.0174), Tregs (r = 0.5317, p = 0.0436), and negatively correlated with the percentage of CD4+ T cells (r = − 0.5989, p = 0.0303." (PMID 32808188, 2021). "HIV-1 integration sites were preferentially found in highly expressed genes and overrepresented in cancer-related genes, and differences between resting versus activated CD4+ T cells and on versus off ART periods were not significant." (PMID 33784259, 2021). "In multiple human cancers such as lung, breast, pancreatic, gastric cancers and melanoma, TLShigh tumors harbor more activated, cytotoxic or naïve CD8+ T cells together with CD4+ T cells which are skewed to a Th1 and/or Th17 phenotype when compared to TLSlow tumors." (PMID 34122434, 2021). "In addition, CELF2 expression was also significantly associated with infiltration levels of B cells in 25 cancers, CD4+ T cells in 29 cancers, CD8+ T cells in 33 cancers, macrophages and DCs in 29 cancers and neutrophils in 32 cancers." (PMID 34288370, 2021). "It is worth noting this paper did not consider the equally important CD4+ response, which would provide valuable insight into the viability of this targeted strategy as an anti-cancer treatment." (PMID 34276688, 2021). "Moreover, CD4 T cells secrete IFN-γ, driving the remodeling of CD4 and CD8 T cells, and enhancing their anti-cancer effector functions." (PMID 34290401, 2021). "We found that Rap1b expression had significant correlation with infiltrating levels of B cells in 21 types of cancer, CD4 + T cells in 18 types of cancer, CD8 + T cells in 24 types of cancer, neutrophil in 27 types of cancer, macrophage in 26 types of cancer and dendritic in 26 types of cancer." (PMID 34346294, 2021). "CD4+ T cells, CD8+ T cells, and macrophages were more key-related immune cells, indicating that SENP1 might be introduced as a potential target for cancer immunotherapy." (PMID 34276383, 2021). "Two additional markers, PD‐1 and PD‐L1, present on both CD4+ (7C) and CD8+ T (7D) cells, have a pivotal role in establishing efficient immunotherapeutic approaches, after it was demonstrated that their inhibition can stop cancer progression." (PMID 34709744, 2021).